ZBTB39 (zinc finger and BTB domain containing 39)
Description:
May be involved in transcriptional regulation.
Synonyms: KIAA0352; ZNF922
Tractability: PROTAC: UniProt records ubiquitination sites on it; ubiquitination databases record sites on it.
Gene: Protein-coding gene on chromosome 12 (56,998,836 to 57,006,546, reverse strand). Ensembl gene ENSG00000166860.
Subcellular location: Nucleus
Subcellular location (Human Protein Atlas): Vesicles
Gene Ontology:
Molecular function: protein binding; DNA-binding transcription repressor activity, RNA polymerase II-specific; RNA polymerase II cis-regulatory region sequence-specific DNA binding
Biological process: negative regulation of transcription by RNA polymerase II; regulation of cytokine production; regulation of immune system process
Cellular component: nucleoplasm; nucleus
Genetic constraint (gnomAD): Loss-of-function variants: 25 observed, 41.31 expected, observed/expected ratio (o/e) 0.61, 90% interval 0.44 to 0.85. The upper end of that interval is the gene's LOEUF score, 0.85, which puts it in group 3 of 6, group 1 being the genes least tolerant of losing a copy. Missense variants: 891 observed, 958.85 expected, observed/expected ratio (o/e) 0.93, 90% interval 0.88 to 0.98. Synonymous variants: 373 observed, 378.87 expected, observed/expected ratio (o/e) 0.98, 90% interval 0.9 to 1.07.
Homologues: Orthologues: chimpanzee ZBTB39 (99% identical), macaque ZBTB39 (98% identical), guinea pig ZBTB39 (92% identical), dog ZBTB39 (92% identical), rabbit ZBTB39 (90% identical), pig ZBTB39 (90% identical), rat Zbtb39 (89% identical), mouse Zbtb39 (89% identical), tropical clawed frog zbtb39 (59% identical), zebrafish zbtb39 (38% identical), Caenorhabditis elegans ztf-16 (8% identical), Caenorhabditis elegans sdz-12 (6% identical), and 2 more. Paralogues in human: ZNF521 (15% identical), ZNF462 (14% identical), ZNF423 (14% identical), ZNF786 (13% identical), ZNF445 (12% identical), ZNF211 (11% identical), ZNF597 (10% identical).
Diseases named in the same sentence as ZBTB39 in open-access papers:
ZBTB39 is named in the same sentence as 1 disease in open-access papers, as found by Europe PMC text mining. Sharing a sentence is not in itself a finding about the gene and the disease. The quoted sentences say what the papers report.
migraine (1 paper, 2025). "Our novel findings also implicate UFL1 and ZBTB39 in migraine chronification - UFL1 stabilizes inflammatory proteins, and ZBTB39 epigenetically modifies pain-related genes." (PMID 40826382, 2025).